SLC11A2 (solute carrier family 11 member 2)
Description:
Proton-coupled metal ion symporter operating with a proton to metal ion stoichiometry of 1:1. Selectively transports various divalent metal cations, in decreasing affinity: Cd(2+) > Fe(2+) > Co(2+), Mn(2+) >> Zn(2+), Ni(2+), VO(2+). Essential for maintenance of iron homeostasis by modulating intestinal absorption of dietary Fe(2+) and TF-associated endosomal Fe(2+) transport in erythroid precursors and other cells (By similarity). Enables Fe(2+) and Mn(2+) ion entry into mitochondria, and is thus expected to promote mitochondrial heme synthesis, iron-sulfur cluster biogenesis and antioxidant defense (By similarity). Can mediate uncoupled fluxes of either protons or metal ions.
Synonyms: DMT-1; DCT1; DMT1; NRAMP2; FLJ37416; AHMIO1
Tractability: Small molecule: a structure with a bound ligand is known; a high-quality ligand is known; it belongs to a druggable protein family. Antibody: UniProt places it where antibodies can reach, with high confidence; its Gene Ontology location is reachable by antibodies, with high confidence; UniProt predicts a signal peptide or a membrane-spanning region. PROTAC: UniProt records ubiquitination sites on it; its protein half-life has been measured; a small molecule that binds it is known.
Target class: SLC11 family of proton-coupled metal ion transporters; Electrochemical transporter; SLC superfamily of solute carriers; Transporter
Gene: Protein-coding gene on chromosome 12 (50,979,401 to 51,028,566, reverse strand). Ensembl gene ENSG00000110911.
Subcellular location: Early endosome membrane (Isoform 1); Apical cell membrane; Late endosome membrane (Isoform 2); Lysosome membrane; Cell membrane; Extracellular vesicle membrane; Cell membrane (Isoform 3); Mitochondrion outer membrane; Golgi apparatus, trans-Golgi network membrane; Recycling endosome membrane
Subcellular location (Human Protein Atlas): Mitochondria
Pathways (Reactome):
Transport of small molecules: Iron uptake and transport; Metal ion SLC transporters
Disease: Defective SLC11A2 causes hypochromic microcytic anemia, with iron overload 1 (AHMIO1)
Gene Ontology:
Molecular function: cadmium ion binding; cadmium ion transmembrane transporter activity; copper ion transmembrane transporter activity; ferrous iron transmembrane transporter activity; iron ion transmembrane transporter activity; lead ion transmembrane transporter activity; manganese ion transmembrane transporter activity; protein binding; solute:proton symporter activity; transition metal ion transmembrane transporter activity; cobalt ion transmembrane transporter activity; nickel cation transmembrane transporter activity; metal ion transmembrane transporter activity
Biological process: cadmium ion transmembrane transport; copper ion transport; iron ion transmembrane transport; iron ion transport; lead ion transport; manganese ion transport; multicellular organismal-level iron ion homeostasis; response to iron ion; intracellular iron ion homeostasis; intracellular manganese ion homeostasis; iron import into cell; metal ion transport; cobalt ion transport; copper ion transmembrane transport; manganese ion transmembrane transport; nickel cation transmembrane transport; proton transmembrane transport
Cellular component: apical part of cell; apical plasma membrane; basal part of cell; cytoplasm; cytoplasmic vesicle; early endosome; early endosome membrane; extracellular vesicle; late endosome membrane; lysosomal membrane; membrane; mitochondrial outer membrane; mitochondrion; nucleus; paraferritin complex; perinuclear region of cytoplasm; plasma membrane; recycling endosome; vacuole; brush border membrane; endosome membrane; recycling endosome membrane; endosome; Golgi apparatus
Genetic constraint (gnomAD): Loss-of-function variants: 35 observed, 59.46 expected, observed/expected ratio (o/e) 0.59, 90% interval 0.45 to 0.78. The upper end of that interval is the gene's LOEUF score, 0.78, which puts it in group 3 of 6, group 1 being the genes least tolerant of losing a copy. Missense variants: 441 observed, 632.52 expected, observed/expected ratio (o/e) 0.7, 90% interval 0.64 to 0.75. Synonymous variants: 212 observed, 233.26 expected, observed/expected ratio (o/e) 0.91, 90% interval 0.81 to 1.02.
Gene-disease validity (ClinGen):
ClinGen rates the evidence that SLC11A2 causes each of these diseases.
microcytic anemia with liver iron overload (autosomal recessive): Definitive. Congenital hypochromic microcytic anemia with progressive liver iron overload paradoxically associated with normal to moderately elevated serum ferritin levels has been described in three unrelated patients.
Homologues: Orthologues: chimpanzee SLC11A2 (99% identical), macaque SLC11A2 (95% identical), rat Slc11a2 (91% identical), rabbit SLC11A2 (91% identical), dog SLC11A2 (90% identical), mouse Slc11a2 (90% identical), guinea pig SLC11A2 (87% identical), pig SLC11A2 (85% identical), tropical clawed frog slc11a2 (75% identical), zebrafish slc11a2 (30% identical). Paralogues in human: SLC11A1 (61% identical).
Diseases named in the same sentence as SLC11A2 in open-access papers:
SLC11A2 is named in the same sentence as 77 diseases in open-access papers, as found by Europe PMC text mining. Sharing a sentence is not in itself a finding about the gene and the disease. The quoted sentences say what the papers report.
anemia (18 papers, 2012 to 2024). A reduction in the number of red blood cells, the amount of hemoglobin, and/or the volume of packed red blood cells. "This study aimed to investigate the association of both mutations 1285G-Cand 1246C-T, in the SLC11A2 gene, and the etiopathogenesisof anemia refractory to iron supplementation in patients undergoingbariatric surgery using Roux-en-Y gastric bypass (RYGB)." (PMID 35730874, 2022). "A previous genetics case study has also associated a mutation in SLC11A2 with a slight increase in serum Fe level in severe anemia and the hepatic Fe overload phenotype." (PMID 35327526, 2022). "Iron deficiency through a knockout of iron import proteins like transferrin receptor (Tfrc) or Dmt1 (Slc11a2) causes anaemia and embryonic or early postnatal lethality in mice." (PMID 31015568, 2019). "Similarly, mice with global deletion of the Slc11a2 gene are born anemic, although iron deficiency anemia in DMT1 knock-out mice is more severe than that observed in animals homozygous for the G185R mutation." (PMID 34573364, 2021). "A mutation in SLC11A2 has been documented in patients with anemia and hepatic iron overload." (PMID 28424608, 2017). "Slc11a2-deficient mice also exhibit severe anemia after birth." (PMID 22363754, 2012). "Eight patients suffering from the rare disease hypochromic microcytic anemia have been described so far to be harboring mutations in the SLC11A2 gene (OMIM #206100; Anemia, hypochromic microcytic, with iron overload 1, AHMIO1)." (PMID 35457224, 2022). "Variants at DUOX2, F5, SLC11A2 and TMPRSS6 associate with iron deficiency anemia, while variants at TF, HFE, TFR2 and TMPRSS6 associate with iron overload." (PMID 33536631, 2021). "Contrariwise, strenuously exercised rats have shown under-expression of duodenal SLC11A2, heme-carrier protein 1, and SLC40A1, which may partially explain the reduced Fe absorption stress-associated stress anemia after intensive exercise." (PMID 35327526, 2022). "After excluding all known causes responsible for iron deficiency anaemia we searched for mutations in SLC11A2 and TMPRSS6 that could explain the severe anaemia in these children." (PMID 22509377, 2012). "Given the wealth of publications describing mutations in two genes (SLC11A2 and TMPRSS6) being associated with iron deficiency anaemia, we initially hypothesized that mutations in these two candidate genes were the reason for this anaemia." (PMID 22509377, 2012).
iron deficiency (18 papers, 2004 to 2026). "We speculate that the accumulation of ferritin‐bound iron induces cytoplasmic iron deficiency, which would upregulate SLC11A2/DMT1 expression, thereby leading to further iron incorporation into SH‐SY5YΔWDR45 cells." (PMID 34837396, 2022). "The mRNA of the transferrin receptor (Tfrc) and the divalent metal transporter-1 (DMT1), known as Slc11a2, contain an IRE in their 3′ untranslated region and are upregulated in iron deficiency." (PMID 33553263, 2020). "The lack of a 3′ UTR IRE, as found in Slc11a2, therefore allows Cybrd1 levels to be up-regulated via HIF-2α under both copper and iron deficiency." (PMID 23555700, 2013).
iron overload (7 papers, 2015 to 2025). "Mutations in SLC11A2 cause an ultra-rare hypochromic microcytic anemia with iron overload (AHMIO1), which has been described in eight patients so far." (PMID 35457224, 2022). "So far, all published cases but two with mutations in the SLC11A2 gene presented with liver iron overload." (PMID 35457224, 2022). "The phenotype of recessive IDA with low iron stores that we report with the rare 3.5 kb deletion within SLC11A2 is different from the previously reported recessive hypochromic anemia with iron overload associated with this gene." (PMID 33536631, 2021). "Biallelic mutations in SLC11A2 cause autosomal recessive hypochromic microcytic anemia with iron overload but there is no mention of any hearing impairment." (PMID 25759012, 2015).
breast carcinoma (5 papers, 2019 to 2025). "The cancer-promoting role of SLC11A2 has been demonstrated in colon and breast cancer, which attracted our attention." (PMID 36670142, 2023). "Transferrin, TFRC and SLC11A2, which are responsible for importing iron into cells, are also expressed at higher levels in breast carcinoma than normal tissues, while the iron exporter SLC4A1 exhibited lower expression." (PMID 33292585, 2020). "The twofold difference in SLC11A2 expression levels between MDA-MB-231 and MCF-10A cells supports the breast cancer cell-specific effect of MCS." (PMID 40570957, 2025).
colon cancer (4 papers, 2013 to 2024). "SLC11A2 is a key protein that aids the absorption of iron and its influence extends to breast and colon cancer progression." (PMID 39050579, 2024). "The Oncomine database shows that SLC11A2 mRNA was expressed at high levels in the brain and central nervous system tumors, lymphoma, colon cancer, and leukemia compared to normal tissues." (PMID 36670142, 2023).
hemochromatosis (4 papers, 2012 to 2017). A disorder of iron metabolism characterized by a triad of HEMOSIDEROSIS; LIVER CIRRHOSIS; and DIABETES MELLITUS. "For example, activation of SLC11A2 in the brain was associated with toxic iron accumulation, autophagy and cell death in mouse models of Parkinson disease whereas pharmacological modulation of SLC11A2 activity can reverse hepatic iron overload in mouse models of hemochromatosis." (PMID 22509377, 2012).
Parkinson disease (4 papers, 2012 to 2024). A progressive degenerative disorder of the central nervous system characterized by loss of dopamine producing neurons in the substantia nigra and the presence of Lewy bodies in the substantia nigra and locus coeruleus. "Increased SLC11A2 activity can lead to excessive manganese uptake, contributing to neurodegenerative disorders such as Parkinson’s disease, impacting immune function, and potentially causing severe toxicity from manganese accumulation." (PMID 39238930, 2024). "Moreover, CC haplotype for SNPs 1254T/C IVS34+44C/A is associated with Parkinson's disease susceptibility, while variant alleles on several SLC11A2 SNPs are associated with iron anemia." (PMID 27355037, 2014).
diabetes (3 papers, 2013 to 2024). "We also found that two IO-related genes including TRFC and SLC11A2, were down-regulated in patients with diabetes and were closely associated with genes related to insulin-secretion." (PMID 37344885, 2023). "Several predicted interactions were observed, many of them encompassing genes involved in the pathogenesis of diabetes, for instance miR-30e targeting IL1A and IRS2, miR-181a targeting IL1A, miR-223 targeting SLC11A2, miR-29b targeting ID1, miR-21 targeting CCL20, and many others." (PMID 24279768, 2013).
endometrial cancer (3 papers, 2022). Primary or metastatic malignant neoplasm involving the endometrium (mucous membrane that lines the endometrial cavity). "None of the tested genetic polymorphisms (rs1695 in GSTP1 and rs224589 in SLC11A2) were found to be associated with endometrial cancer risk." (PMID 35893933, 2022). "This was the first study to analyze functional polymorphism in SLC11A2 gene in endometrial cancer patients." (PMID 35893933, 2022). "We analyzed whether polymorphisms rs1695 in GSTP1 and rs224589 in SLC11A2 genes are associated with the risk of endometrial cancer." (PMID 35893933, 2022). "According to published studies, the SLC11A2 polymorphism is directly related to the risk of endometrial cancer, indicating that SLC11A2 might participate in the progression of tumors." (PMID 36532744, 2022). "It has been shown that SLC11A2 expression is upregulated in endometrial cancer, and is correlated with a better prognosis." (PMID 36117156, 2022).
microcytic anemia (3 papers, 2021 to 2025). Anemia in which the red blood cell volume is decreased. "Here, we report two new patients with hypochromic microcytic anemia due to mutations in the SLC11A2 gene, being the ninth and tenth world-wide identified cases, and we study the pathophysiologic consequences of the DMT1 G75R mutation." (PMID 35457224, 2022). "Conversely, SLC11A2 loss of function or reduced expression results in microcytic anemia." (PMID 40355757, 2025).
ovarian carcinoma (2 papers, 2023). A malignant neoplasm originating from the surface ovarian epithelium. "This study suggests that SLC11A2 may be a potential therapeutic target and combined diagnostic biomarker for ovarian cancer." (PMID 36670142, 2023). "The aim of this study was to investigate the effectiveness of SLC11A2 as a therapeutic target and marker for ovarian cancer." (PMID 36670142, 2023). "The immunohistochemical prognostic curves of advanced ovarian cancer show that patients with high SLC11A2 expression have shorter OS." (PMID 36670142, 2023). "Using tissue SLC11A2 mRNA transcript levels as a predictor of ovarian cancer, the area under the curve AUC was 0.749, and the confidence interval CI was 0.708–0.791." (PMID 36670142, 2023). "Survival analysis showed that the high SLC11A2 mRNA expression group had poor prognosis than the low expression group in ovarian cancer patients, and the results of the 4 arrays were similar." (PMID 36670142, 2023). "The results showed that ovarian cancers with high SLC11A2 mRNA expression had shorter 5-year PFS and MST." (PMID 36670142, 2023). "The relative concentration value of SLC11A2 protein in plasma exosomes of ovarian cancer patients was significantly higher than that of healthy and benign ovarian disease groups." (PMID 36670142, 2023). "This study showed that high SLC11A2 mRNA and protein expression in ovarian cancer tissues tends toward a worse prognosis." (PMID 36670142, 2023). "Data from two independent GENT microarray platforms showed that SLC11A2 transcript levels were significantly increased in ovarian cancer compared with normal ovarian tissue (GPL570, P < 0.001, Log2FC = 0.207; GPL96, P < 0.001, Log2FC = 0.399)." (PMID 36670142, 2023). "The expression level of SLC11A2 mRNA in ovarian cancer tissues was higher in the 3 databases (noted by red boxes)." (PMID 36670142, 2023). "Transwell cell migration assays showed that the expression level of SLC11A2 was positively correlated with the migration ability of ovarian cancer cell lines." (PMID 36670142, 2023). "The three main pathological classifications of epithelial ovarian cancer are shown in the figure, and statistical analysis shows that the expression of the SLC11A2 protein is significantly increased in ovarian cancer." (PMID 36670142, 2023). "We counted the apoptosis ratio of SKOV3 cells induced by cisplatin, and the results showed that the knockdown of SLC11A2 significantly increased the proportion of ovarian cancer apoptosis induced by a certain concentration of cisplatin." (PMID 36670142, 2023). "Combined analysis of ovarian cancer tissues from the TCGA database and normal ovarian tissues from the GTEx database revealed elevated levels of SLC11A2 mRNA in ovarian serous carcinoma." (PMID 36670142, 2023). "The results showed that the knockdown of SLC11A2 significantly improved the survival rate and replication efficiency of ovarian cancer cells (P = 0.006)." (PMID 36670142, 2023). "Platinum alkylating agents-based chemotherapy is the first-line chemotherapy for ovarian cancer, so we used cisplatin (platinum chemotherapy drugs) as an inducer to detect the effect of SLC11A2 knockdown on ovarian cancer cells." (PMID 36670142, 2023). "Setting p < 0.001 as the threshold, the two GENT microarray data were intersected to obtain SLC11A2 mRNA with elevated transcript levels in blood, breast, colon, liver, lung, and ovary cancers and reduced transcript levels in kidney cancer." (PMID 36670142, 2023). "Finally, the protein expression of SLC11A2 in serum, ovarian cancer tissue, normal ovary, and normal fallopian tube tissue, and protein expression level in the serum of ovarian cancer patients were detected." (PMID 36670142, 2023). "Then, the biological functions of SLC11A2 were validated in four ovarian cancer cell lines." (PMID 36670142, 2023). "Knockdown of SLC11A2 reduced ovarian cancer migration and increased cisplatin-induced apoptosis." (PMID 36670142, 2023).
ovarian carcinoma (continued). "Meanwhile, we validated the effect of SLC11A2 on ovarian cancer cells in vitro." (PMID 36670142, 2023). "In the GENT database, SLC11A2 expression was upregulated in several cancer types, including adrenal, bladder, bone, breast, endometrial, colon, lung, lymphoma, prostate, gastric, and ovarian cancer." (PMID 36670142, 2023). "Compared with cancer tissues, SLC11A2 mRNA expression was elevated in ovarian cancer tissues." (PMID 36670142, 2023). "We used the Kaplan-Mayer plotter web tool to obtain the mRNA expression of SLC11A2 in ovarian cancer corresponding to 4 different probe matrices." (PMID 36670142, 2023). "The following heat map shows the expression level of SLC11A2 in ovarian cancer." (PMID 36670142, 2023). "Knockdown of SLC11A2 increased cisplatin-induced apoptosis in ovarian cancer cells." (PMID 36670142, 2023). "Knockdown of SLC11A2 could significantly inhibit the migration ability of ovarian cancer cells." (PMID 36670142, 2023). "Finally, we collected ovarian cancer clinical tissues, serum, and plasma exosomes and used immunohistochemistry, Elisa, and liquid chromatography-mass spectrometry (LC–MS) to validate the test efficacy of SLC11A2." (PMID 36670142, 2023). "Serum SLC11A2 may help improve the detection rate of ovarian cancer." (PMID 36670142, 2023). "Conversely, 8 genes showed increased expression in ovarian cancer tissues, including LCN2, CP, TFR2, LRP2, MELTF, LTF, SLC11A2, and STEAP3." (PMID 38186569, 2023). "In the context of iron import, except for SLC11A2, most genes did not exhibit a significant correlation with the varying stages of ovarian cancer." (PMID 38186569, 2023). "Although the HR is not high as it looks, considering that most of the ovarian cancer nests are diffusely expressed in the immunohistochemical results and normal ovaries are completely negative, indicated that SLC11A2 is highly expressed in the vast majority of ovarian cancers." (PMID 36670142, 2023).
adenomyosis (1 paper, 2025). The growth of endometrial tissue inside the muscular wall of the uterine corpus. "Genes that promote ferroptosis, such as ACSL1, ALOX15, STEAP3, and SLC11A2, were upregulated in adenomyosis." (PMID 40911580, 2025).